OR7H2P (olfactory receptor family 7 subfamily H member 2 pseudogene)
Gene: Unprocessed pseudogene on chromosome 5 (101,816,475 to 101,816,780, reverse strand). Ensembl gene ENSG00000251261.
Diseases named in the same sentence as OR7H2P in open-access papers:
OR7H2P is named in the same sentence as 1 disease in open-access papers, as found by Europe PMC text mining. Sharing a sentence is not in itself a finding about the gene and the disease. The quoted sentences say what the papers report.
Anxiety (1 paper, 2025). Intense feelings of nervousness, tension, or panic often arise in response to interpersonal stresses. "The olfactory receptor genes OR4L1 and OR7H2P are linked to sensory pathways associated with anxiety traits, while ATXN1 (6p22.3) connects cognitive and physical genetic risks." (PMID 40125487, 2025).